TIMP2 (TIMP metallopeptidase inhibitor 2)
Diseases named in the same sentence as TIMP2 in open-access papers (continued):
Sharing a sentence is not in itself a finding about the gene and the disease.
tumor (continued). "The transcriptomic analysis of the Groft scientific group showed a positive correlation between TIMP1 expression and a negative correlation of TIMP4 expression with tumor grade and malignant behavior, while the expression of TIMP3 and TIMP2 remained unchanged." (PMID 38474106, 2024). "TIMP2 is known to be a SASP factor and shown to function in tumor suppression and has not yet been identified in exosomes." (PMID 38589887, 2024). "For TIMP-2, the included studies typically reported a reduction in expression in PrCa, including a negative correlation of the expression to tumor grade and metastasis, with promoter hypermethylation representing one mechanism by which the expression could be lost." (PMID 33808504, 2021). "HSA/TIMP-2 has no inhibitory effect on MMP-2 activity in vitro and in vivo; nevertheless HSA/TIMP-2 demonstrated a prominent anti-proliferation effect on tumor cells in cancer xenografts." (PMID 22545131, 2012). "Our results show that HSA/TIMP-2, which does not inhibit MMP-2 activity or MT1-MMP expression in vivo, acts to promote anti-tumor and anti-angiogenesis activity through the downregulation of MMP-2 expression." (PMID 22545131, 2012). "Plasma concentrations of MMP1, MMP3, MMP9, TIMP2, and MTC1 did not correlate to tumour stage and grade, but also to lymph node involvement or distant metastasis (data not indicated)." (PMID 16901349, 2006). "Plasma concentrations of MMP1, MMP3, MMP9, TIMP2, and the MTC1 did not correlate to tumour stage, grade, lymph node involvement, or distant metastasis." (PMID 16901349, 2006). "Additionally, our results show the tumor stage, nodal involvement, presence of distant metastases, and tumor resectability, but not serum MMP-2 nor TIMP-2 as the significant prognostic factors in CRC patients in univariate analysis." (PMID 24395652, 2014). "Separate analyzes of MMP1, MMP2, MMP3, MMP9, TIMP1, TIMP2, and MTC1 in plasma do not allow a prognostic prediction for tumour grading, staging, or metastasis, but certain combinations could be very helpful." (PMID 16901349, 2006). "By RT-PCR, TIMP-2 and TIMP-3 expression did not change with tumour grade." (PMID 11437402, 2001). "Also, the potential for TIMP-2 to either promote or inhibit cell growth could be affected by the concentration of TIMP-2 and the presence or absence of growth factors such as EGF or PDGF in the tumor microenvironment." (PMID 26556867, 2015).
cancer (205 papers, 1992 to 2025). A tumor composed of atypical neoplastic, often pleomorphic cells that invade other tissues. "Conversely, MDA− microvesicles were enriched for metalloprotease inhibitor-2 (TIMP-2), which is associated with inhibition of matrix metalloproteases and decreased cancer cell invasion." (PMID 37649089, 2023). "Among the hub genes, except for TIMP2, the other 9 genes were associated with the induction of various cancer hallmarks." (PMID 36879084, 2023). "The expression of TIMP2 in different cancers was analyzed by Oncomine, TCGA, and GTEx databases, and mutation status of TIMP2 in cancers was then verified using the cBioPortal database." (PMID 36304987, 2022). "Alternatively, Timp2 deficiency is associated with abnormal motor function and cognitive dysfunction, as well as unfavorable outcomes in cancer development." (PMID 36624735, 2022). "These implicated that TIMP2 was involved in multiple different cancer-promoting processes, aiding discoveries in identifying therapeutic targets regarding the TIMP-metalloproteinase-substrate network." (PMID 36304987, 2022). "TIMP1 is commonly found in cancer cells and is associated with a poor prognosis; TIMP2 inhibits the mitogenic response of human microvascular endothelial cells to growth factors; and TIMP4 is an MMP inhibitor in human platelets." (PMID 33960555, 2021). "Enzyme-linked immunosorbent assays (ELISAs) showed that TIMP-2 concentrations in the serum of patients with NSCLC were significantly lower in patients with stage II/III cancer than in patients with stage I cancer." (PMID 31061410, 2019). "Previous studies have shown that the MMP-2 (-1306C/T) and TIMP-2 (-418G/C) polymorphisms are involved in the development of many cancers, such as breast, lung, and esophageal and colon cancer." (PMID 31032338, 2019). "The association of the MMP-2 (-1306C/T) and TIMP-2 (-418G/C) polymorphisms with the incidence and development of many cancers has been widely reported." (PMID 31032338, 2019). "This analysis highlights the interconnectivity of the TIMP2 correlating genes, providing further evidence that these cancer-associated changes in gene co-expression share the same drivers." (PMID 31882975, 2019). "And, the amounts of TIMP-2 expression have also been found to be associated with different types of cancer." (PMID 26729052, 2017). "Through integrated analysis of The Cancer Genome Atlas data, TIMP-2 expression was significantly associated with the alteration of driving genes, c-Src activation, and PI3-kinase/AKT pathway activation." (PMID 26556867, 2015). "We searched PubMed (Medline) and EMBASE web databases to cover all studies based on relationship of TIMP2 -418 G>C polymorphism and risk of cancer until October 2013." (PMID 25136829, 2014). "In this meta-analysis, we aimed to evaluate the potential association between TIMP2 -418 G>C polymorphism and cancer risk." (PMID 25136829, 2014). "The results from the published studies based on the association between TIMP2 -418 G>C polymorphism and cancer risk are inconsistent." (PMID 25136829, 2014). "We pooled the data from all ten studies together and it yielded into 2225 cancer cases and 2532 control subjects, for appraisal of overall association between TIMP2 -418 G>C polymorphism and cancer risk." (PMID 25136829, 2014). "In recent years, genetic variants of the TIMP2 gene and its role in the etiology of several types of cancer have been studied exhaustively, but the outcomes are inconclusive and contradictory." (PMID 25136829, 2014). "Low and high amounts of TIMP2 expression have been found to be associated with different types and metastasis of cancer and in several cases it has been shown to be associated with a poor patient prognosis." (PMID 25136829, 2014). "There is also growing evidence from clinical-pathological analyses to support that loss of TIMP-2 expression occurs in many types of human cancer, in particular at the late stages of tumor progression." (PMID 26056585, 2014).
cancer (continued). "Studies either showing TIMP2 polymorphism to predict survival in cancer patients or considering TIMP2 variants as an indicators for response to therapy were excluded straightaway from this meta-analysis." (PMID 25136829, 2014). "In our system, EFEMP1 expression was up-regulated in TIMP-2 overexpressing cells, rendering a 6.507 decrease fold-change in cancer development and metastasis-associated functions." (PMID 26056585, 2014). "TIMP-2 expression by cancer cells was associated with peritumoral lymphovascular invasion, and expression of HSP-27, cathepsin D and uPA by stromal cells." (PMID 16776850, 2006). "For example, higher MMP-2/TIMP-2 ratios were associated with recurrences in patients with bladder or uterine cervix cancer." (PMID 16776850, 2006). "Collectively, these findings suggested that assessing TIMP-2 polymorphisms, in addition to its expression levels, could serve as a valuable biomarker for various types of cancer." (PMID 38276258, 2023). "Furthermore, we evaluated the association of TIMP2 with levels of immune cell infiltration in cancers." (PMID 36304987, 2022). "Most studies on TIMP-2 polymorphisms have been performed in relation to cancers." (PMID 36430677, 2022). "Therefore, we validated a panel of cancer-associated genes by qPCR analysis and found TIMP2 mRNA levels to be increased in OCT-treated BON cells, an effect that is likely mediated through miR-221." (PMID 36555512, 2022). "Thus, our aim was to explore the genomic mutation profiling of TIMP2 in pan cancer, regarding the analysis of TIMP2, which was exhibited by the cBioPortal database." (PMID 36304987, 2022). "Furthermore, in both of the cancer cell lines, ND caused an increased level of IL-8 and a decreased level of TIMP-2, whereas GO caused only decreased levels of TIMP-2 and ICAM-1 proteins." (PMID 34829982, 2021). "Genetic variation of TIMP-2 is also associated with the risk of the malignant tumor and cancer." (PMID 31275061, 2019). "The roles of TIMP-1 and TIMP 2 (both are inhibitors of matrix metalloproeteinases) in MDSC generation are less clear, though serum TIMP-1 levels are associated with shorter survival in many types of cancer and TIMP-2 has been shown to be a negative regulator of MDSCs in mice." (PMID 28666020, 2017). "Instead, some have suggested that high TIMP-2 levels may promote tumourigenecity, which has been strengthened by the association of high TIMP-2 levels with poor prognosis in various human cancers, including breast." (PMID 27756325, 2016). "In order to derive more precise results, we performed the current meta-analysis to assess whether an association exists between the TIMP2 gene polymorphism and risk of developing cancer." (PMID 25136829, 2014). "However, there are contradicting findings from clinical studies addressing the association of TIMP-2 expression in the development and progression of several cancers." (PMID 26056585, 2014). "One of the possible explanations is that TIMP2 gene has several other SNPs and each polymorphism to cancer risk might be due to linkage disequilibrium (LD)." (PMID 25136829, 2014). "Considering the vital role of TIMP2 in carcinogenesis, several molecular epidemiological case-control studies have been performed to investigate the possible association between the TIMP2 -418 G>C polymorphism and cancer susceptibility in various neoplasm in different populations." (PMID 25136829, 2014). "In some of the selected studies, the controls were not uniformly defined and some studies included patient with benign disease which may contribute to the TIMP2 gene mutation and development of various cancers." (PMID 25136829, 2014). "Moreover, WA not only suppressed levels of the tumorigenesis and metastasis-associated vimentin protein, it also caused elevated levels of cancer cell inhibitory, extra cellular matrix-associated TIMP2 protein." (PMID 22912669, 2012).
cancer (continued). "In the context of TNBC, EZH2 plays a pivotal role in its progression by promoting the migration and invasion of cancer cells through the regulation of the TIMP2-MMP-2/-9 pathway." (PMID 39120328, 2024). "Tissue inhibitor of metalloproteinase-2 (TIMP-2) has a role in remodeling the extracellular matrix to promote cancer progression." (PMID 38725484, 2024). "Increased TIMP-2 levels positively correlate with MMP-2 activation and poor prognoses in cancer patients, with a clear association between TIMP-2 levels and cancer cell migration." (PMID 39684484, 2024). "CCX832 inhibits these effects by downregulating tissue inhibitors of metalloproteinases (TIMP-1 and TIMP-2), highlighting chemerin’s role in enhancing cancer cell invasiveness." (PMID 39590835, 2024). "They summarized that the essence of the role of TIMP2 in cancer development is based on the protein’s concentration within individual tissues." (PMID 38474106, 2024). "Nakopoulou and Jones observed comparable immuno-activity of TIMP-2 in breast primary cancer cells and fibroblasts, while Garbett and colleagues reported heightened TIMP-2 expression in tumor cells compared to fibroblasts and inflammatory cells." (PMID 38276258, 2023). "TIMP-2 is an endogenous inhibitor of matrix metalloproteinases that are involved in cancer development and progression." (PMID 38276258, 2023). "Since some of these hsa-miR-429 targets either have antiangiogenic functions (e.g., TIMP2) or are cancer-type specific, further studies are necessary in order to understand how this miRNA modulates angiogenesis in different types of cancer." (PMID 37296866, 2023). "To get a better understanding of the enigmatic and sophisticated role of the TIMP2 expression in cancer, we explored the functional state of TIMP2 across various cancer types based on the CancerSEA database." (PMID 36304987, 2022). "In contrast, when NF-κB translocation and transcriptional activity are inhibited, the expression of MMP2 and MMP9 is reduced and the expression of TIMP-2 is increased, further inhibiting the migration of cancer cells." (PMID 35770085, 2022). "In this study, we had a sophisticated understanding of TIMP2 in pan cancer on basis of data-mining analysis from various databases, providing a theoretical basis for cancer diagnosis and prognosis." (PMID 36304987, 2022). "Altogether, our study was conducted using diverse public databases and displayed the expression and clinical significance of TIMP2 in cancers." (PMID 36304987, 2022). "Numerous studies have reported that MMP-1, MMP-2, and MMP-9 enzymes and TIMP-1 and TIMP-2 inhibitors play an active role in angiogenesis, local invasiveness, and metastatic potential of malignant tumors." (PMID 36551933, 2022). "Upregulated TIMP2 expression level in cancer tissues probably played a crucial part in the occurrence of cancers." (PMID 36304987, 2022). "A recent study sought to establish a link between MMP-2, MMP-7, and their inhibitor, TIMP-2, in adult and pediatric cancer." (PMID 36250005, 2022). "MMP-2, MMP-7, MMP-9, TIMP-1, and TIMP-2 research has received considerable attention since they play a number of roles in cancer." (PMID 36250005, 2022). "Kaplan Meier curves displayed elevated expression of TIMP2 was an unfavorable prognostic factor for cancer patients, including OS (overall survival) and DFS (disease-free survival) prognosis." (PMID 36304987, 2022). "At first, we compared the mRNA expression of TIMP2 in 20 types of cancer with that in normal tissues through Oncomine databases." (PMID 34678879, 2021). "Otherwise, we have proposed a new role of TIMP2/KLF2 in the formation of cancer-induced pre-metastatic niche, and provided new insights into the formation of the metastasis niche." (PMID 34497265, 2021). "In both of the cancer cell lines, lower levels of TIMP-2 and the intracellular adhesion molecule, ICAM-1, were noted." (PMID 34829982, 2021).
cancer (continued). "TIMP-1 and TIMP-2 proteins have been found in EVs derived from cancer cells, bone marrow mesenchymal stem cells and also in pregnant women." (PMID 32610589, 2020). "The medium levels of TIMP-2 and MMP-2/TIMP-2 complex in serum were higher in healthy women than in cases with a malignant tumor." (PMID 32751899, 2020). "SNAIL leads to the induction of TIMP-3, and similarly, although independent of the metalloproteinase inhibitory function, the expression of TIMP-1 induces TWIST1 to negatively regulate E-cadherin in cancer cells, while TIMP2 upregulates this cadherin." (PMID 33419373, 2020). "The effect of the dung beetle glycosaminoglycan known as an anti-aging and anti-cancer substance was related to upregulation of TIMP2 and the glycosaminoglycan’s anti-inflammatory activity." (PMID 33333870, 2020). "We focused our in-depth analyses on breast and lung tumors, since we have found that TIMP2 can deliver therapeutic effects in murine models of these cancers and that they formed the nucleus of our identified study cluster." (PMID 31882975, 2019). "Recent studies in our lab have shown that TIMP2 is a promising candidate for biological cancer therapy." (PMID 31882975, 2019). "As a part of our ongoing effort for the identification of natural products with anti-cancer effects, we present here first time that miR-93 up-regulated in OS tissues and cell line, directly repressing TIMP2 expression." (PMID 31383784, 2019). "Conversely, in cancer tissues, including NSCLC, the expression of TIMP-2 is constantly low, thereby promoting the invasion of cancer cells." (PMID 31061410, 2019). "Kaplan-Meier survival analysis was conducted by 5-year overall cumulative survival, which revealed that low TIMP-2 or high MMP-9 expression in cancer tissues was correlated with a worse OS in CRC patients (P < 0.001 and P < 0.001, respectively, log-rank test)." (PMID 31293204, 2019). "Our earlier analysis of TIMP2 co-expression profiles identified genes that correlate with TIMP2 in cancers, highlighting a need to understand the TIMP2 co-expressed genes in normal tissues." (PMID 31882975, 2019). "On the other hand, TIMP2 suppresses their activity and is therefore deemed to own inhibitory effect on cancer metastasis." (PMID 31649548, 2019). "This suggests that if any of these co-expressed genes modulate TIMP2 function, then it is a common occurrence in carcinomas." (PMID 31882975, 2019). "To further disclose the potential functions of TIMP2 in cancers, we performed GSEA, a robust computational method to identify a-priori defined set of genes in a special phenotype." (PMID 29941993, 2018). "On the other hand, conflicting evidences were present by different studies about the prognostic role of TIMP2 in the same type of cancer, such as breast, lung, cervical, ovarian, and bladder cancer." (PMID 29941993, 2018). "In GC, TIMP2 was declared to express in cancer, mesenchymal or immune cells, with the clinical role still ambiguous." (PMID 29941993, 2018). "Results for the expressions of TIMP1,2, upon 24 h actein treatment, demonstrated that actein significantly upregulated the expressions of TIMP1 and TIMP2, thereby resulting in reduced cancer progression and cancer cell invasion." (PMID 30618758, 2018). "This undesirable feature of TIMP-2 has always been a deterring factor in its development as a therapeutic agent to treat MT1-MMP-related diseases such as cancers." (PMID 28186971, 2017). "ADAM12 inhibitory antibodies or genetically altered tissue inhibitor of metalloproteinases 2 (TIMP2) for specifically blocking ADAM12 or recombinant ADAM12 prodomain still need to be investigated in animal models of cancer cell migration." (PMID 28260841, 2017).